DDB1 (damage specific DNA binding protein 1)
Description:
Protein, which is both involved in DNA repair and protein ubiquitination, as part of the UV-DDB complex and DCX (DDB1-CUL4-X-box) complexes, respectively. Core component of the UV-DDB complex (UV-damaged DNA-binding protein complex), a complex that recognizes UV-induced DNA damage and recruit proteins of the nucleotide excision repair pathway (the NER pathway) to initiate DNA repair. The UV-DDB complex preferentially binds to cyclobutane pyrimidine dimers (CPD), 6-4 photoproducts (6-4 PP), apurinic sites and short mismatches. Also functions as a component of numerous distinct DCX (DDB1-CUL4-X-box) E3 ubiquitin-protein ligase complexes which mediate the ubiquitination and subsequent proteasomal degradation of target proteins. The functional specificity of the DCX E3 ubiquitin-protein ligase complex is determined by the variable substrate recognition component recruited by DDB1. DCX(DDB2) (also known as DDB1-CUL4-ROC1, CUL4-DDB-ROC1 and CUL4-DDB-RBX1) may ubiquitinate histone H2A, histone H3 and histone H4 at sites of UV-induced DNA damage. The ubiquitination of histones may facilitate their removal from the nucleosome and promote subsequent DNA repair. DCX(DDB2) also ubiquitinates XPC, which may enhance DNA-binding by XPC and promote NER. DCX(ERCC8) (the CSA complex) plays a role in transcription-coupled repair (TCR). The DDB1-CUL4A-DTL E3 ligase complex regulates the circadian clock function by mediating the ubiquitination and degradation of CRY1. DDB1-mediated CRY1 degradation promotes FOXO1 protein stability and FOXO1-mediated gluconeogenesis in the liver (By similarity). By acting on TET dioxygenses, essential for oocyte maintenance at the primordial follicle stage, hence essential for female fertility (By similarity). Maternal factor required for proper zygotic genome activation and genome reprogramming (By similarity).
Synonyms: DDBa; XPE-BF; XPCe; XAP1; UV-DDB1; WHIKERS; XPE
Tractability: Small molecule: an approved drug acts on it; a structure with a bound ligand is known; a high-quality ligand is known; it has a high-quality binding pocket. PROTAC: UniProt records ubiquitination sites on it; ubiquitination databases record sites on it; its protein half-life has been measured; a small molecule that binds it is known.
Gene: Protein-coding gene on chromosome 11 (61,299,447 to 61,342,596, reverse strand). Ensembl gene ENSG00000167986.
Subcellular location: Cytoplasm; Nucleus
Subcellular location (Human Protein Atlas): Nucleoplasm; End piece; Mid piece; Principal piece
Pathways (Reactome):
DNA Repair: DNA Damage Recognition in GG-NER; Dual Incision in GG-NER; Dual incision in TC-NER; Formation of Incision Complex in GG-NER; Formation of TC-NER Pre-Incision Complex; Gap-filling DNA repair synthesis and ligation in TC-NER; Recognition of DNA damage by PCNA-containing replication complex; Transcription-Coupled Nucleotide Excision Repair (TC-NER)
Metabolism of proteins: Neddylation
Gene Ontology:
Molecular function: cullin family protein binding; damaged DNA binding; protein binding; protein-containing complex binding; protein-macromolecule adaptor activity; ubiquitin ligase complex scaffold activity; WD40-repeat domain binding; DNA binding; nucleic acid binding
Biological process: biological process involved in interaction with symbiont; cellular response to UV; DNA damage response; epigenetic programming in the zygotic pronuclei; positive regulation by virus of viral protein levels in host cell; positive regulation of protein catabolic process; positive regulation of viral genome replication; proteasomal protein catabolic process; proteasome-mediated ubiquitin-dependent protein catabolic process; protein ubiquitination; regulation of mitotic cell cycle phase transition; spindle assembly involved in female meiosis; ubiquitin-dependent protein catabolic process; UV-damage excision repair; viral release from host cell; cell population proliferation; DNA repair; epigenetic regulation of gene expression; negative regulation of adipose tissue development; nucleotide-excision repair; positive regulation of gluconeogenesis; regulation of apoptotic process; regulation of autophagy; regulation of cell cycle phase transition; regulation of cell population proliferation; and 10 more
Cellular component: chromosome, telomeric region; Cul4-RING E3 ubiquitin ligase complex; Cul4A-RING E3 ubiquitin ligase complex; Cul4B-RING E3 ubiquitin ligase complex; cytoplasm; extracellular exosome; extracellular region; nucleolus; nucleoplasm; nucleotide-excision repair complex; nucleus; protein-containing complex; site of double-strand break
Genetic constraint (gnomAD): Loss-of-function variants: 18 observed, 136.64 expected, observed/expected ratio (o/e) 0.13, 90% interval 0.09 to 0.19. The upper end of that interval is the gene's LOEUF score, 0.19, which puts it in group 1 of 6, group 1 being the genes least tolerant of losing a copy. Missense variants: 825 observed, 1,513.7 expected, observed/expected ratio (o/e) 0.55, 90% interval 0.51 to 0.58. Synonymous variants: 579 observed, 573.46 expected, observed/expected ratio (o/e) 1.01, 90% interval 0.94 to 1.08.
Homologues: Orthologues: dog DDB1 (99% identical), rabbit DDB1 (99% identical), rat Ddb1 (99% identical), mouse Ddb1 (99% identical), pig DDB1 (99% identical), guinea pig DDB1 (99% identical), chimpanzee DDB1 (99% identical), macaque DDB1 (99% identical), tropical clawed frog ddb1 (92% identical), zebrafish ddb1 (89% identical), Drosophila melanogaster pic (61% identical), Caenorhabditis elegans ddb-1 (38% identical). Paralogues in human: CPSF1 (22% identical), SF3B3 (21% identical).
Diseases named in the same sentence as DDB1 in open-access papers:
DDB1 is named in the same sentence as 82 diseases in open-access papers, as found by Europe PMC text mining. Sharing a sentence is not in itself a finding about the gene and the disease. The quoted sentences say what the papers report.
melanoma (9 papers, 2013 to 2023). A malignant, usually aggressive tumor composed of atypical, neoplastic melanocytes. "Despite this, melanoma cells displayed a DDB2 protein induction profile comparable to melanocytes, and two (Sk-Mel-28, Mel-RM) of four melanoma cell lines displayed induction of DDB1 similar to normal melanocytes." (PMID 26913219, 2015). "To date, somatic mutations in XPC, DDB1 and DDB2 have rarely been reported in melanoma tumours." (PMID 29373959, 2018). "In contrast, DOT1L targets the DDB1 gene locus only in melanoma cell lines." (PMID 29343685, 2018). "The transcript levels of XPC, DDB1 and DDB2 were also quantified in melanoma tumours and compared to clinical information." (PMID 27487145, 2016). "Expression of the DNA damage recognition GGR components XPC, DDB1 and DDB2 was significantly higher in melanocytes than melanoma from 4 or 8 to 48 hours after UVB irradiation." (PMID 27487145, 2016). "Given the significantly lower DDB1 and DDB2 transcript expression observed in melanoma cells, this suggests enhanced translation rate or protein stability of DDB1 and DDB2 in melanoma cells." (PMID 26913219, 2015). "We recently reported only a limited induction of XPC, DDB1 and DDB2 GGR transcripts in melanoma cell lines 24 hours after cisplatin treatment suggesting a breakdown in the normal NER response to DNA damage." (PMID 23940574, 2013). "Expression of GGR components XPC, DDB1 and DDB2 was significantly lower in melanoma after UVB." (PMID 27487145, 2016). "We have found that the three GGR components XPC, DDB1 and DDB2 do not respond to UV treatment in melanoma cell lines, resulting in reduced repair of UV-induced DNA damage." (PMID 29373959, 2018). "Expression of GGR components, XPC, DDB1 and DDB2 significantly increased in response to cisplatin in melanocytes but this increase was noticeably absent in melanoma." (PMID 27487145, 2016). "In this first study to investigate NER in melanoma after UVB we have confirmed that GGR is reduced in melanoma by showing delayed repair of both 6-4 PPs and CPDs, particularly in the crucial S-phase of the cell cycle, and lack of induction of XPC, DDB1 and DDB2 after UVB." (PMID 27487145, 2016). "Importantly, DNA repair transcripts PCNA and BRCA1, both of which have previously been reported to regulate DDB1 and DDB2 transcript expression, had significantly higher induction in melanocytes 24 hours after cisplatin treatment but not in the majority of the melanoma cell lines." (PMID 23940574, 2013).
osteosarcoma (9 papers, 2017 to 2024). A usually aggressive malignant bone-forming mesenchymal neoplasm, predominantly affecting adolescents and young adults. "Our results provide evidence for a potential new DCAF11 pathway in which DCAF11 associates with CUL4B and DDB1 to target p21 for proteolysis in human osteosarcoma cells." (PMID 28446751, 2017). "A study found that in human osteosarcoma cells, CUL4B forms an E3 ligase with RBX1 (RING-box 1), DDB1 (DNA damage binding protein 1), and DCAF11 (DDB1 and CUL4 associated factor 11)." (PMID 39062505, 2024). "As another subunit of the DDB protein complex, DDB1 is a tumor-promoting factor, and its expression is upregulated in pancreatic cancer, liver cancer, and osteosarcoma." (PMID 36190612, 2022). "DDB1 can directly interact with Cullin4B (CUL4B) to form the CUL4B-DDB1 complex which promotes ubiquitination and degradation of a variety of tumor suppressor factors hence enhance progression of osteosarcoma." (PMID 34268106, 2021). "Human osteosarcoma exhibits CUL4B overexpression, which interacts with DNA damage binding protein 1 (DDB1) as well as DDB1- and CUL4-associated factor 13 (DCAF13)." (PMID 32984016, 2020). "Our recent study suggests that CUL4B associates with DDB1, RBX1, and DCAF11 to form a unique CRL4BDCAF11 E3 complex in human osteosarcoma cells, and this E3 ligase can specifically target p21Cip1 for degradation, thereby regulating cell cycle progression." (PMID 29377600, 2018). "Here, we demonstrated that CUL4B forms an E3 ligase with RBX1 (RING-box 1), DDB1 (DNA damage binding protein 1), and DCAF11 (DDB1 and CUL4 associated factor 11) in human osteosarcoma cells." (PMID 28446751, 2017). "The CUL4B-Flag immunocomplex from hFOB1.19, U2OS or Saos-2 cells pulled down DCAF4 and DCAF11, but not DCAF1, 8 and 15, indicating that these two DCAFs form complexes with CUL4 and DDB1 in osteosarcoma cells." (PMID 28446751, 2017). "We also observed a significant decrease in CDK2 levels after down-regulation of CUL4B, DDB1 or DCAF11 in osteosarcoma cells, which raised the question of whether DCAF11 is responsible for the degradation of CDK2." (PMID 28446751, 2017). "To determine whether CUL4B can interact with RBX1 and DDB1 in osteosarcoma cells, we first constructed the pCDNA3-CUL4B-Flag vector, which we then transfected into hFOB1.19, U2OS and Saos-2 cells." (PMID 28446751, 2017). "Recently, we found that CUL4B was overexpressed in osteosarcoma and that the activated CUL4B formed an E3 ligase with DDB1, RBX1, and DCAF11, which further ubiquitinated p21 and caused p21 degradation, resulting in the disruption of cell cycle progression." (PMID 29377600, 2018). "As expected, osteosarcoma cells expressing lower levels of CUL4B, DDB1 or DCAF11 exhibited dramatically higher percentages of cells in S phase." (PMID 28446751, 2017). "In summary, our results demonstrate that CUL4B forms an E3 ligase with RBX1, DDB1 and DCAF11 to recognize p21 as a substrate in human osteosarcoma cells." (PMID 28446751, 2017). "To illuminate the molecular function of CUL4B, especially to determine interacting proteins and to identify the substrates of CRL4B E3 ligase in osteosarcoma cells, we first confirmed interactions between CUL4B and RBX1 or DDB1 in vivo and in vitro." (PMID 28446751, 2017). "In addition, the same amount of CUL4B-Flag protein pulled down much more DDB1 and RBX1 protein in U2OS and Saos-2 osteosarcoma cells than in hFOB1.19 cells, suggesting that DDB1 and RBX1 are also upregulated in osteosarcoma cells." (PMID 28446751, 2017). "By examining the protein levels of several DCAFs in osteosarcoma cells, we found that DCAF11 was specifically upregulated, whereas other DCAFs, such as DCAF1, 4, 8, and 15, were not, and we then determined the interactions between DCAF11 and DDB1." (PMID 28446751, 2017).
osteosarcoma (continued). "Knocking down any component of the CRL4BDCAF11 complex, including CUL4B, DDB1 or DCAF11, using short hairpin RNAs (shRNAs) attenuated the ubiquitination level of p21Cip1, inhibited osteosarcoma cell proliferation, led to cell cycle arrest at S phase, and decreased colony formation rate." (PMID 28446751, 2017). "Thus, CDK2 might be only a CUL4B-associated protein, and its down-regulation in osteosarcoma cells expressing lower CUL4B, DDB1 or DCAF11 might not be regulated by DCAF11 but might rather be regulated by p21 induction, as p21 is an inhibitor of CDK2." (PMID 28446751, 2017).
hepatocellular carcinoma (8 papers, 2014 to 2025). A malignant tumor that arises from hepatocytes. "Hepatitis B virus (HBV), which is one of the primary cause of liver diseases such as cirrhosis and hepatocellular carcinoma, uses X protein (HBx) to hijack DDB1–Cul4A complex." (PMID 24522884, 2014). "Expressing DDB1 in hepatoma cells restores HBx-mediated SMC5/6 degradation and enhances cccDNA transcriptional activity." (PMID 38757942, 2024). "Mechanistically, PARG dePARylates damage-specific DNA binding protein 1 (DDB1), thereby up-regulating its auto-ubiquitination and decreasing its stability in hepatocellular carcinoma cells (Ref." (PMID 39375922, 2024). "This stabilization enables DDB1 to degrade its downstream targets, such as c-Myc, thereby promoting hepatocellular carcinoma in mouse xenograft models." (PMID 38447797, 2024). "The deletion of DDB1 abrogates the self-renewing capacity of hepatocytes and results in the compensatory proliferation of DDB1-expressing hepatocytes, thus leading to hepatocellular carcinoma." (PMID 31842285, 2019). "Furthermore, in hepatocellular carcinoma cells, O-GlcNAcylation of PARG enhances the poly(ADP-ribosyl)ation of DNA damage–binding protein 1 (DDB1) and attenuates its autoubiquitination, leading to the stabilization of DDB1." (PMID 38447797, 2024). "HBx binds to DDB1 and interferes with the NER, resulting in the accumulation of DNA mutations in hepatocytes that may contribute to the development of hepatocellular carcinoma (HCC)." (PMID 35100095, 2022). "In hepatocellular carcinoma (HCC) cells, PARG O-GlcNAcylation enhances the poly(ADP-ribosyl)ation of DNA damage-binding protein 1 (DDB1) and attenuates its auto-ubiquitination, thereby stabilizing DDB1 and allowing it to degrade its downstream targets, such as c-Myc." (PMID 37858678, 2023).
lung carcinoma (7 papers, 2020 to 2025). "In conclusion, we demonstrated the involvement of DDB1 in mediating the effect of circ_0004470 on lung cancer progression using multiple experimental models, including malignant transformation of cells, animal models, and clinical samples." (PMID 40157540, 2025). "To elucidate the mechanism by which circ_0004470 regulates DDB1 during lung cancer progression, we performed cotransfection experiments." (PMID 40157540, 2025). "In NNK- and Cd-transformed cells and lung cancer cell lines (A549, H1299, and H446), DDB1 was downregulated and CDT1 was upregulated, consistent with the results in clinical samples." (PMID 40157540, 2025). "Chromatin licensing and DNA replication factor 1 (CDT1), a cell cycle–regulated partner of DDB1, is upregulated in several early precancerous lesions in lung cancer." (PMID 40157540, 2025). "Additionally, circERI3 inhibits DDB1 ubiquitination and regulates PGC-1α transcription through DDB1, thus increasing mitochondrial energy metabolism and ultimately contributing to the development of lung cancer." (PMID 40860147, 2025). "Moreover, significantly higher expression levels of CRBN and DDB1 mRNA were detected in NE lineage lung cancers compared to non-small cell lung cancers (NSCLC), which are representative of non-NE cancers in the lung." (PMID 40551250, 2025). "DDB1 and CUL4 associated factor 13 (DCAF13) is a substrate receptor of the E3 ubiquitin ligase CRL4, but its role in lung cancer remains unknown." (PMID 38163876, 2024). "Further studies are necessary to clarify the involvement of DDB1 and CDT1 in lung cancer progression, as well as their role in the regulation of circ_0004470 associated with lung cancer progression." (PMID 40157540, 2025). "The present study showed that circ_0004470 plays a role in the pathogenesis of lung cancer induced by BPDE via interactions with mRNAs or the XPC and DDB1 proteins." (PMID 40157540, 2025). "Analysis of lung cancer clinical samples showed that the expression of DDB1 was significantly lower in lung cancer tissues than in normal tissues, whereas CDT1 was expressed at high levels in lung cancer tissues (left)." (PMID 40157540, 2025). "These cell lines exhibited significantly higher levels of CRBN and DDB1 protein compared to non-NE lung cancer cell lines." (PMID 40551250, 2025). "Moreover, our previous study has shown deregulation of the genes encoding the NER-related molecular components of the heterodimer DDB complex (DDB1 and DDB2) in patients with lung cancer." (PMID 39766117, 2024). "However, in a set of lung cancer cells, the complex responsible for degrading DLC-1 comprises CULT4, DDB1 and FBXW5 E3 ligases all together, thus suggesting the difference existing in the composition of E3 ligases between cancer cells and hMSCs." (PMID 33148199, 2020). "The ectopic expression of RPMA or RPMN in non-NE lung cancer cell lines (H2023 and HCC827) consistently elevated CRBN and DDB1 expression across all clones achieved, regardless of their basal genetic backgrounds." (PMID 40551250, 2025).
multiple myeloma (7 papers, 2015 to 2025). "Indeed, truncation and point mutations in CRBN and DDB1 were discovered in myeloma cells and patient samples despite the fact that these mutations were rare." (PMID 33392195, 2020). "It should be noted that different myeloma cell lines and primary myeloma cells may have distinct genetic backgrounds, such as mutations and expression level of genes including CRBN, CASP-8, and DDB1, which affect cell proliferation and regulate cell death pathways." (PMID 33392195, 2020). "Nonetheless, the definitive leap for thalidomide and its derivatives was made in proving their efficiency against multiple myeloma and other pathologies, and their mechanism of action, which defined the E3 ligase CRBN and the DNA-damage-binding protein 1 (DDB1) as the endogenous targets." (PMID 33339292, 2020).